CD164 (CD164 molecule)
Diseases named in the same sentence as CD164 in open-access papers (continued):
Sharing a sentence is not in itself a finding about the gene and the disease.
tumor (17 papers, 2006 to 2025). "Silencing CD164 expression clearly reduces tumor cell growth and causes apoptosis, according to functional studies." (PMID 40692786, 2025). "Clinicopathological correlation analysis additionally indicated that CD164 upregulation was significantly associated with tumor grade and metastasis." (PMID 32719743, 2020). "Wound and healing assay and transwell array were used to investigate the associations of CD164 with migration and invasion of tumor cells." (PMID 30022623, 2018). "CD164 immunohistochemistry revealed the existence of significantly positive associations between CD164 expression and tumor size (p=0.001), lymph node involvement (p=0.001), and tumor cell grading (p=0.043)." (PMID 28903328, 2017). "The clinicopathological correlation analysis showed that the upregulation of CD164 protein was significantly associated with tumor grade and metastasis." (PMID 24094005, 2013). "All these results implied that CD164 may be a risk marker, which played a role in tumor progression." (PMID 30022623, 2018). "Immunohistochemistry of tumor tissues from 115 patients diagnosed with BC in third central hospital of Tianjin and provincial hospital affiliated to Shandong university was performed to investigated the association between the expression of CD164 and clinical‐pathological characters of patients." (PMID 30022623, 2018). "RNA sequencing and GSEA showed that CD164 regulates proliferation, metabolism, migration, and adhesion pathways while suppressing tumor-promoting pathways and activating immune-related pathways." (PMID 40692786, 2025). "Subsequent correlation analysis between gene expression levels and immune cell abundances provided preliminary insights into CD164’s potential regulatory role in the tumor immune microenvironment." (PMID 40692786, 2025). "GSVA and GSEA enrichment studies were carried out to investigate the molecular pathways by which CD164 affects tumor development even more." (PMID 40692786, 2025). "Once detached from the primary tumor mass, the adhesion and invasion of tumor cells are facilitated by chemokines and adhesion molecules, such as CD164 and αvβ3 integrins." (PMID 38260135, 2023). "One cluster (C2 Tumor cells) expressed stem-related genes (SOX4 and CD164); the other (C3-Tumor cells) expressed proliferative genes (MKI67 and MCM2)." (PMID 36788228, 2023). "CD164 has also been found to promote lung tumor-initiating cells with stem cell activity and determine tumor growth and drug resistance via Akt/mTOR signaling." (PMID 32364222, 2020). "There was a positive correlation between CD164 H-scores and both tumor type and grade (p < 0.001; p for trend < 0.001 for both comparisons)." (PMID 31007847, 2019). "In non-small cell lung cancer, the tumor suppressor miR-124 targeted CD164 and suppressed tumor proliferation and aggressiveness." (PMID 31007847, 2019). "The same study reported that several stem cell-specific transcriptional factors, such as Nanog, Oct4 and Sox-2, were also activated by CD164 overexpression and this activation increased tumor cell stemness and tumorigenesis." (PMID 31007847, 2019). "Then, to further explore the mechanism of CD164 in tumor proliferation, some proliferation‐related proteins were identified and detected." (PMID 30022623, 2018). "The immunohistochemistry (IHC) was performed to evaluate the associations between the expression level of CD164 and clinical‐pathological features of patients, and IHC was used to analyze the relationship between CD164 and CXCR4 in tumor tissues." (PMID 30022623, 2018). "The roles of CD164 in tumor cells and tissues were investigated by in vitro and in vivo experiments." (PMID 30022623, 2018). "To further demonstrate the roles of CD164 in tumor progression, we researched the influence of CD164 on tumor growth and metastasis in mice." (PMID 30022623, 2018). "Then, the functions of CD164 in tumor proliferation, migration, and invasion were studied in vivo and in vitro." (PMID 30022623, 2018).
tumor (continued). "Colony formation and MTT arrays were performed to investigate the impact of CD164 on the proliferation of tumor cells." (PMID 30022623, 2018). "The data showed that by knocking down CD164, the abilities of migration and invasion of tumor cells were decreased (P < .05)." (PMID 30022623, 2018). "Rapamycin inhibited sphere formation in vitro and xenograft tumor growth from higher CD164 expression cells in vivo." (PMID 28903328, 2017). "Emerging evidence indicated that CD164 was found to function as a receptor that increased tumor metastasis and hematopoietic stem cell trafficking." (PMID 28903328, 2017). "In conclusion, we have provided evidence that CD164 promotes the growth of lung tumor-initiating cells with stem cell properties and induces tumor growth and drug resistance through Akt/mTOR signaling." (PMID 28903328, 2017). "CD164 was first identified as MGC-24 and cloned as a carrier of a peanut agglutinin-binding site, a tumor-associated carbohydrate marker expressed in human gastric carcinoma cells." (PMID 16859559, 2006). "Likewise, increased CD164 expression, a co-receptor for LCMV infection, is linked to malignant transformation and tumor progression." (PMID 41086811, 2025). "In addition, CD164 expression in lung tissue of tumor patients was significantly higher than that in matched control samples." (PMID 32364222, 2020). "Significantly, CD164 regulates CXCR4 function in different tumor types." (PMID 32719743, 2020). "It is interesting that ATX, LPAR1, and LPAR5 are higher in the immune-high tumor (Cd14-, Cd68-, Cd164-, and Cd3E-high) group, but LPAR2.3 are higher in the immune-low group, suggesting the complex regulatory roles of the ATX–LPA axis in the tumor–immune system interaction." (PMID 31658655, 2019). "In conclusion, the results revealed that silencing of CD164 could inhibit the proliferation of tumor cells by regulating the expression of proliferation‐related proteins such as Ki67 and PCNA." (PMID 30022623, 2018). "In summary, the results in our study were consisted with most of previous studies, which revealed that CD164 functioned as a tumor promoter and could promote the progression of tumors in vivo and in vitro." (PMID 30022623, 2018). "In vitro, by silencing of CD164, the proliferation, migration, and invasion of tumor cells were inhibited significantly by regulating related proteins such as Ki67, proliferating cell nuclear antigen, matrix metalloproteinases‐2, and matrix metalloproteinases‐9." (PMID 30022623, 2018). "In all, our results revealed that CD164, as a tumor promoter, played an essential role in tumor progression, which may become a potential treatment target of BC patients." (PMID 30022623, 2018). "This study explores whether CD164 promotes tumor-initiation and drug resistance through the stem cell property." (PMID 28903328, 2017). "We disclosed that CD164 might be an imperative molecule linking tumor-initiating and chemoresistance because it might activate either the downstream signaling of mTOR or ABC transporters." (PMID 28903328, 2017). "The correlation between CD164 expression and tumor stage prompted us to investigate whether CD164 increased malignant transformation in normal lung epithelial cell, BEAS2B cells." (PMID 28903328, 2017). "To investigate the functional roles of CD164 in tumorigenicity, we used shRNA targeting CD164 gene expression to investigate whether the downregulation of CD164 in ovarian cells could inhibit tumor growth and increase the survival time of xenografted mice." (PMID 24094005, 2013). "Overexpressing CD164 in hOSE cells may have the ability to induce tumor cell growth, proliferation, migration and self-renewal mediated through the induction of SDF-1α and CXCR4, which activates the SDF-1α/CXCR4 signaling pathway." (PMID 24094005, 2013).
tumor (continued). "Transcriptomic sequencing data supporting this result showed that CD164 inhibition activates several immune-related pathways, including neutrophil extracellular trap formation and interactions between cytokine-cytokine receptors, so improving the anti-tumor immune response." (PMID 40692786, 2025). "Of note, the reduction was more evident in hypoxia condition (p = 0.005, one-way ANOVA), indicating that the impact of reduced expression of the IGF2BP3/CD164/CXCR4 oncogenic pathway may be stronger in the tumor microenvironment compared to physiological conditions." (PMID 32719743, 2020). "Silencing of CD164 could inhibit the proliferation, migration, and invasion of tumor cells." (PMID 30022623, 2018). "CD164 may be a target gene in the AP-1 pathway and plays crucial roles in tumor development." (PMID 21999799, 2011). "Furthermore, the correlation between staining intensity and sites of frequent metastasis and CXCL12 staining is further evidence that CD164 may be involved in tumor localization." (PMID 16859559, 2006). "Further closely related to drug metabolism, excretion, and pharmacodynamics, GSEA analysis also revealed that CD164 modulates pathways, including AMPK signaling, butyrate metabolism, and circadian rhythm, so influencing tumor progression." (PMID 40692786, 2025). "The C2-tumor cluster had high autophagy (ATG5, MAP1LC3B), high plasticity (SOX4, CD164) and low mTORC1 activity (RPS6, MLST8), characteristics of early paligenosis (stages 1-2)." (PMID 36788228, 2023). "Further experiments are warranted to elucidate the conflicting role of CD164 in SDF-1/CXCR4-dependent signaling in GBM, its impact on autophagy and apoptosis, and the ensuing effects on tumor growth and survival." (PMID 31007847, 2019). "We excluded markers that are known to be ubiquitously expressed on all nucleated cells (e.g. HLA) or on tumour cells (e.g. CD47) and focused our attention on five markers (CD57, CD59, CD81, CD164 and CD98) for further interrogation." (PMID 27590276, 2016). "Sites that exhibited a high propensity for tumor metastasis and high levels of CXCL12 exhibited intense CD164 immunoreactivity." (PMID 16859559, 2006). "The pathway analyses particularly demonstrated CD164’s dual role in promoting oncogenic signaling (PI3K-Akt, TGF-β) while suppressing tumor-suppressive metabolic pathways (AMPK, butyrate metabolism), providing mechanistic insight into its pro-tumorigenic effects." (PMID 40692786, 2025). "We found that CD164 was uniformly expressed at the mRNA level on CD26− and CD26+ cells, but the protein was only detectable on the surface of specific subsets of cells, with the percentages of CD26−CD164+ cells increasing with increasing tumor burden." (PMID 40723261, 2025). "The peripheral levels of TRIM44, CTSZ, CD164, and TIMP1 can stimulate granulocyte production in mouse bone marrow, and high levels of TIMP1 are positively correlated with increased immune infiltration levels of tumor-infiltrating lymphocytes." (PMID 40524208, 2025). "Because CXCR4 is induced in EWS cells exposed to hypoxia, a common condition of human tumor microenvironment, we investigated the contribution of the IGF2BP3/CD164/CXCR4 axis on CXCL12-evoked biological responses of EWS cells under normoxic (21% O2) or hypoxic conditions (1% O2)." (PMID 32719743, 2020). "Both of the nucleuses and cytoplasm (mainly) of tumor cells were dyed and the typical strong and weak staining of CD164 was shown, while CD164 was negative in the normal bladder tissues." (PMID 30022623, 2018). "In addition, a co‐expression was found between CD164 and CXCR4 in tumor tissues." (PMID 30022623, 2018). "Hence, we propose that CD164 overexpression increases cell proliferation and chemoresistance via the PI3K/Akt/mTOR pathway, resulting in the conversion of normal human bronchial epithelial cell to tumor-initiating cells." (PMID 28903328, 2017).
tumor (continued). "However, CD164 mechanisms of action in EWS cells were not further characterized and its impact on tumor progression has never been evaluated." (PMID 32719743, 2020).
infection (7 papers, 2010 to 2024). The state of being infected such as from the introduction of a foreign agent such as serum, vaccine, antigenic substance or organism. "For both LCMV and LASV, sialylation of the lysosomal host factor at a specific N-linked glycosylated residue by ST3GAL4 is required for infection, N104 in the case of CD164 and LCMV and N76 in the case of LAMP1 and LASV." (PMID 35235462, 2022). "Further characterization of CD164 by deletion mapping and alanine mutagenesis suggests that the cysteine-rich domain, particularly a single critical N-linked glycosylation site, is required for CD164-mediated infection." (PMID 35502904, 2022). "Through combined biochemical genetic and virological studies, we defined the central cysteine-rich domain (CRD) of CD164 and a specific, sialylated N-linked glycan within that domain required for infection." (PMID 35235462, 2022). "All of the variants were expressed to similar levels to WT CD164, and with the exception of substitution N104Q, all restored infection." (PMID 35235462, 2022). "To examine whether loss of CD164 affected infection of cells mediated by other arenavirus GPs, we infected A549ΔCD164 cells with a panel of VSV-arenavirus chimeras." (PMID 35235462, 2022). "Cytotrophoblasts bathe in maternal blood and are an initial contact site for pathogens, suggesting that CD164 is present in tissue structures and locations amenable for transplacental infection of the developing fetus." (PMID 35502904, 2022). "Since knockout of CD164 demonstrated near ablation of infection, we chose to follow up on this protein to explore its role in the viral life cycle." (PMID 35502904, 2022). "Unlike DAG1, to which LCMV strains show a range of affinities, all five LCMV strains tested here required CD164 for infection in human cells." (PMID 35502904, 2022). "Infection of A549 cells with a recombinant LCMV-Armstrong engineered to express GFP, LCMV-2A-GFP, also show a marked reduction in infection upon inactivation of CD164, ST3GAL4, or SLC35A1." (PMID 35235462, 2022). "In both human lines, A549 and 293T, deletion of CD164 reduced infection by 99% and 95%, respectively, while the effect in the mouse cell line 3T6 was moderate (41% reduction)." (PMID 35502904, 2022). "Deletion of CD164 reduced infection by all four pseudotyped viruses by 78% to 99% in both human cell lines, indicating a strong CD164 dependency in all cases." (PMID 35502904, 2022). "Given the documented role of LCMV with respect to transplacental human infections, CD164 expression was investigated in human placental tissue and placental cell lines." (PMID 35502904, 2022). "The ablation of infection due to mutagenesis of the N-linked glycosylation site suggests that the cysteine-rich domain, including a critical asparagine amino acid, is required for CD164-mediated infection by LCMV." (PMID 35502904, 2022). "Human fetal vulnerability to LCMV led us to hypothesize that CD164 plays a role in transplacental infection." (PMID 35502904, 2022). "Perturbations of multiple host genes impeded infection including the lysosomal sialomucin, CD164." (PMID 35235462, 2022). "Infection of HeLaΔCD164 cells was restored upon lentiviral complementation with human or mouse CD164, verifying that CD164 is specifically inactivated in cells and that mouse and human CD164 facilitate infection." (PMID 35235462, 2022). "As with A549 cells, inactivation of CD164 inhibits infection by VSV-LCMV." (PMID 35235462, 2022). "Lentiviral vector complementation restored infection, providing experimental support that the overall size or shape of MD2 contributes to the role of CD164 in LCMV infection." (PMID 35235462, 2022). "Given the apparent unique dependency of LCMV on CD164 and the practical implications of its involvement in transplacental infection, further exploration of the mechanistic details by which congenital LCMV can be prevented through blocking CD164 is warranted." (PMID 35502904, 2022).
infection (continued). "CD164 localizes to the cell surface and late-stage endosomes, consistent with the LCMV entry route for successful infection." (PMID 35502904, 2022). "Collectively, these data directly demonstrate a role of CD164, SLC35A1, and ST3GAL4 in LCMV-GP–mediated infection at the entry step and validate their importance for infection with WT LCMV." (PMID 35235462, 2022). "Using a LCMV-pseudotyped virus and an infection period of 3 weeks, the authors identified seven host factors important for LCMV entry, four of which (CD164, ST3GAL4, SLC35A1, and MAN1A2) were contained within the set of 37 factors identified in our live virus screen." (PMID 35502904, 2022). "Consistent with the ability to mediate cell–cell fusion, cell-surface CD164 facilitates LCMV-GP–mediated infection upon exposure of surface-bound virus to pH 4.5 but not the N104Q CD164 mutant." (PMID 35235462, 2022). "Among these, knockout of the sialomucin CD164, a heavily glycosylated transmembrane protein, was found to ablate infection with multiple LCMV strains but not other hemorrhagic mammarenaviruses in several cell types." (PMID 35502904, 2022). "The anti-CD164 MAb N6B6, which was demonstrated to bind a conformationally dependent backbone epitope encompassing the cysteine-rich domain between the two mucin domains, blocked infection by rLCMV-mCherry in a dose-dependent manner." (PMID 35502904, 2022). "Preincubation of these cells with anti-CD164 MAb N6B6 blocked rLCMV-mCherry infection, with a treatment of 25 μg/mL N6B6 reducing the detection of mCherry-positive cells by 84% and 125 μg/mL reducing infection further by 94%." (PMID 35502904, 2022). "We performed similar experiments on the inhibition of Ha-CoV-2 infection by SHREKs, and found that in addition to PSGL-1, CD164, TIM-1, MUC1, and MUC4 also inhibited the infection of Ha-CoV-2 virus; The MUC4 vector had the strongest inhibition among these SHREKs." (PMID 34064525, 2021). "Infection of VSV-DAND and VSV-LUNK were reduced in A549ΔCD164 cells, thus demonstrating that CD164 is a host factor specific to LCMV-related viruses but not other pathogenic human arenaviruses." (PMID 35235462, 2022).
bacterial infection (1 paper, 2023). "visgun (vsg), which is widely expressed in Drosophila hemocytes, was indicated as a CD164 orthologue and has been recently established as a crucial marker for phagocytosis and immune activation upon Photorhabdus luminescens bacterial infection." (PMID 38113249, 2023).
CD164 also shares sentences with these, for which no sentence is quoted: acute myeloid leukemia (1 paper); adenocarcinoma (1); astrocytoma (1); benign tumor (1); bone cancer (1); brain cancer (1); chronic obstructive pulmonary disease (1); colorectal cancer (1); COVID-19 (1); interstitial lung disease (1); large cell carcinoma (1); lymph node metastasis (1); lymphoma (1); Nonsyndromic Hearing Impairment (1); pancreatic cancer (1); small cell lung carcinoma (1); squamous cell carcinoma (1); squamous cell lung carcinoma (1); thyroid cancer (1).